IGSF10 (immunoglobulin superfamily member 10)
Description:
Involved in the control of early migration of neurons expressing gonadotropin-releasing hormone (GNRH neurons) (By similarity). May be involved in the maintenance of osteochondroprogenitor cells pool (By similarity).
Synonyms: CMF608; FLJ25972
Tractability: Antibody: UniProt places it where antibodies can reach, with high confidence; its Gene Ontology location is reachable by antibodies, with high confidence; UniProt predicts a signal peptide or a membrane-spanning region. PROTAC: ubiquitination databases record sites on it.
Gene: Protein-coding gene on chromosome 3 (151,425,384 to 151,461,186, reverse strand). Ensembl gene ENSG00000152580.
Subcellular location: Secreted
Subcellular location (Human Protein Atlas): Vesicles; Predicted to be secreted
Gene Ontology:
Biological process: regulation of neuron migration
Cellular component: extracellular region; non-collagenous component of interstitial matrix
Genetic constraint (gnomAD): Loss-of-function variants: 122 observed, 132.71 expected, observed/expected ratio (o/e) 0.92, 90% interval 0.79 to 1.07. The upper end of that interval is the gene's LOEUF score, 1.07, which puts it in group 4 of 6, group 1 being the genes least tolerant of losing a copy. Missense variants: 3,272 observed, 3,301.6 expected, observed/expected ratio (o/e) 0.99, 90% interval 0.96 to 1.02. Synonymous variants: 1,176 observed, 1,205.9 expected, observed/expected ratio (o/e) 0.98, 90% interval 0.93 to 1.02.
Homologues: Orthologues: chimpanzee IGSF10 (99% identical), macaque IGSF10 (94% identical), dog IGSF10 (78% identical), pig IGSF10 (77% identical), rabbit IGSF10 (75% identical), guinea pig IGSF10 (72% identical), mouse Igsf10 (65% identical), rat Igsf10 (64% identical), tropical clawed frog igsf10 (46% identical), zebrafish igsf10 (37% identical). Paralogues in human: MXRA5 (32% identical), HMCN2 (18% identical), DSCAM (13% identical), DSCAML1 (13% identical), SDK1 (11% identical), SDK2 (11% identical), ROBO1 (9% identical), ROBO2 (9% identical), PTPRQ (9% identical), ROBO3 (9% identical), NEO1 (9% identical), DCC (8% identical), and 24 more.
Diseases named in the same sentence as IGSF10 in open-access papers:
IGSF10 is named in the same sentence as 57 diseases in open-access papers, as found by Europe PMC text mining. Sharing a sentence is not in itself a finding about the gene and the disease. The quoted sentences say what the papers report.
lung carcinoma (11 papers, 2020 to 2025). "In the current study, we demonstrated low expression of IGSF10 in lung tumour tissues and demonstrated that low expression of IGSF10 was significantly associated with overall survival in lung cancer patients according to the TCGA‐LUAD database." (PMID 41447338, 2025). "A comprehensive bioinformatics analysis revealed that, the decreased expression of immunoglobulin superfamily member 10 (IGSF10) was associated with the shortened overall survival duration of patients with lung cancer." (PMID 36212131, 2022). "However, the molecular mechanism underlying the modulation of IGSF10 in lung cancer still needs further understanding, and the present study is aiming to explore this important issue." (PMID 41447338, 2025). "Knocking out IGSF10 significantly enhances lung cancer cell proliferation, promotes cell-matrix adhesion, and activates the integrin-β1/FAK pathway." (PMID 40598621, 2025). "This activation is marked by increased expression of integrin-β1, p-FAK, and p-AKT, illustrating IGSF10’s role in inhibiting lung cancer metastasis and invasion." (PMID 40598621, 2025). "Overall, our findings further clarified the role of IGSF10 in lung cancer cells and theoretically suggested new avenues for the presumable IGSF10‐targeting therapy." (PMID 41447338, 2025). "Our findings clarified the specific role of IGSF10 in LUAD, and theoretically suggested new avenues for the presumable IGSF10‐targeting therapy of lung cancer in the future." (PMID 41447338, 2025). "Nevertheless, there have been few reports on the relevance of IGSF10 to the pathogenesis of lung cancer in the past, although we preliminarily confirmed its involvement in the cellular function of lung cancer." (PMID 41447338, 2025). "IGSF10 is a protein belonging to the immunoglobulin superfamily known to regulate the migration and invasive ability of lung cancer cells." (PMID 38398114, 2024). "A recent study investigated that IGSF10 expression was considerably reduced in lung cancer, and knockdown of IGSF10 promoted malignant progression of lung cancer cells." (PMID 36685968, 2022). "IGSF10, a member of the immunoglobulin superfamily, was a novel prognostic biomarker for breast cancer and lung cancer." (PMID 34559577, 2021). "Oncomine database analysis showed that expression of IGSF10 was significantly reduced in lung cancer tissues compared to the corresponding normal lung tissues." (PMID 34351868, 2021). "Our previous study demonstrated that IGSF10 functions as a tumor suppressor in lung cancer via integrin-β1/FAK signaling pathway." (PMID 34351868, 2021). "In our previous study, we demonstrated that IGSF10 played a tumor suppressor role in lung cancer and was a potential prognostic factor for lung cancer patients." (PMID 34351868, 2021). "The expression of IGSF10 is downregulated in lung cancer tissues, and decreased expression of IGSF10 correlated with a poor prognosis for patients with lung cancer." (PMID 33150070, 2020). "Recently, a systematic pan‐cancer analysis using a variety of bioinformatic ways concludes that IGSF10 could serve as a novel prognostic marker and attainable immunotherapy for several malignancies, including lung cancer." (PMID 41447338, 2025). "However, the pathogenesis of lung cancer and the regulatory mechanisms of IGSF10 are still poorly understood." (PMID 41447338, 2025). "Furthermore, we elucidated the precise impact of IGSF10 on the biological functions of lung cancer cells, that is, highly expressed IGSF10 can suppress lung cancer cell migration and growth, as well as tumorigenesis." (PMID 41447338, 2025).
lung carcinoma (continued). "The contrasting finding regarding IGSF10 highlights the heterogeneity within lung cancer and suggests that the role of miR-106b-5p might indeed differ between various histological subtypes, such as adenocarcinoma versus squamous cell carcinoma." (PMID 41155295, 2025). "IGSF10 expression is significantly decreased in lung cancer patients." (PMID 38398114, 2024). "We then downloaded IGSF10 expression data in lung cancer datasets from the GEO database and observed downregulation of IGSF10 expression in the LUAD and LUSC samples from the GSE19188 dataset as well as lung cancer tissues in the GSE31210 and GSE32863 datasets." (PMID 34351868, 2021). "This suggests that IGSF10 regulates both adaptive and innate immune responses in lung cancer." (PMID 34351868, 2021). "Interestingly, one study reported that miR-106b-5p inhibits the growth and progression of lung adenocarcinoma cells by downregulating IGSF10, indicating that its role might vary depending on the specific histological subtype within lung cancer." (PMID 41155295, 2025). "Inhibition of IGSF10 expression by IGSF10-small interfering RNA was demonstrated to inhibit cancer cell proliferation, enhance adhesion between cells and matrix, and increase the survival rate of patients with lung cancer by activating the integrin-β1/FAK pathway." (PMID 36517562, 2022). "However, the regulatory role of IGSF10 in lung cancer remains unclear." (PMID 34351868, 2021). "Ling and colleagues claimed that IGSF10 knockout promotes the development of lung cancer and that IGSF10 mainly activates the integrin-β1/FAK pathway in lung cancer." (PMID 33150070, 2020).
breast carcinoma (5 papers, 2020 to 2025). "The potential mechanisms and pathways associated with IGSF10 in breast cancer were explored by performing a gene set enrichment analysis (GSEA)." (PMID 33150070, 2020). "In the present study, we identified IGSF10 as a potential prognostic biomarker for breast cancer and described a possible mechanism underlying its role in the tumorigenesis of breast cancer." (PMID 33150070, 2020). "In breast cancer, IGSF10 plays a role in DNA repair, cell cycle regulation, and glycolysis, and is associated with the PI3K/Akt/mTOR and mTORC1 signaling pathways." (PMID 40598621, 2025). "Seven hundred patients with breast cancer in the TCGA cohort were analyzed to further confirm the correlation between IGSF10 expression and breast cancer." (PMID 33150070, 2020). "More importantly, IGSF10 was an independent prognostic factor for better outcomes in patients with breast cancer." (PMID 33150070, 2020). "IGSF10 was expressed at higher levels in the normal breast epithelial cell line MCF10A than in the breast cancer cell lines." (PMID 33150070, 2020). "We collected the clinical information from 700 patients with breast cancer in The Cancer Genome Atlas (TCGA), and analyzed the relationship between IGSF10 expression and the clinicopathological features and survival outcomes of these patients." (PMID 33150070, 2020). "The multivariate analysis identified IGSF10 as an independent prognostic factor for patients with breast cancer." (PMID 33150070, 2020). "Consistent with the results from TCGA database, IGSF10 expression was substantially downregulated in breast cancer tissues." (PMID 33150070, 2020). "By applying real-time quantitative polymerase chain reaction (qRT-PCR) and immunohistochemistry (IHC), the expression of IGSF10 in breast cancer cells and tissues was detected." (PMID 33150070, 2020). "According to TCGA data, qRT-PCR and IHC experiments, levels of the IGSF10 mRNA and protein were significantly decreased in breast cancer tissues." (PMID 33150070, 2020). "The multivariate Cox regression analysis of TCGA patients with breast cancer showed that IGSF10 was an independent prognostic factor for OS (HR = 1.793, 95% CI [1.141–2.815], P = 0.011) and RFS (HR = 2.298, 95% CI [1.317–4.010], P = 0.003)." (PMID 33150070, 2020). "In the present study, we explored the role of IGSF10 in breast cancer by analyzing TCGA data and performing RT-qPCR and IHC." (PMID 33150070, 2020). "Based on the analysis of the data in the UALCAN database, we found that IGSF10 expression correlated with the molecular subtype of breast cancer." (PMID 33150070, 2020). "Based on our results, the IGSF10 mRNA was expressed at higher levels in adjacent normal tissues than in breast cancer tissues." (PMID 33150070, 2020). "This study revealed a clear relationship between IGSF10 expression and the tumorigenesis of breast cancer for the first time." (PMID 33150070, 2020). "In the present study, the expression of IGSF10 in collected breast cancer tissues was examined using qRT-PCR and IHC." (PMID 33150070, 2020). "Furthermore, another research determined that the expression of IGSF10 was down-regulated in breast cancer tissues, and IGSF10 expression was related to good prognosis." (PMID 36685968, 2022). "Our data indicated that IGSF10 expression was significantly downregulated in breast cancer tissues." (PMID 33150070, 2020). "We examined the expression of the IGSF10 mRNA in 1095 patients with breast cancer in TCGA database." (PMID 33150070, 2020). "However, to our knowledge, no studies have reported the possible functions and mechanisms of IGSF10 in breast cancer." (PMID 33150070, 2020). "In the present study, potential biological roles and signaling pathways that may be related to IGSF10 expression in breast cancer were analyzed by conducting a GSEA." (PMID 33150070, 2020). "Overall, we suggested a novel role for IGSF10 in breast cancer." (PMID 33150070, 2020).
breast carcinoma (continued). "Moreover, the survival analysis indicated that patients with breast cancer presenting higher IGSF10 expression experienced prolonged OS and RFS." (PMID 33150070, 2020). "Consistent with our results, multiple datasets in the Oncomine database suggested that IGSF10 expression was down-regulated in breast cancer tissues (absolute fold change > 2) including TCGA Breast, Karnoub Breast, Zhao Breast, Richardson Breast 2, and Finak Breast datasets." (PMID 33150070, 2020). "Accordingly, IGSF10 may play a crucial role in breast cancer and have the potential to be targeted by anticancer therapy." (PMID 33150070, 2020). "In summary, IGSF10 was expressed at a low level in breast cancer." (PMID 33150070, 2020). "Potential mechanisms and signaling pathways that may be related to the ability of IGSF10 to regulate the development of breast cancer were explored by conducting a GSEA." (PMID 33150070, 2020). "However, further studies are needed to elucidate the role of IGSF10 in breast cancer and the detailed mechanisms by which IGSF10 modulates these related signaling pathways." (PMID 33150070, 2020). "Therefore, further studies are needed to understand the mechanism of IGSF10 in breast cancer." (PMID 33150070, 2020). "Currently, the role and possible mechanism of IGSF10 in breast cancer remain unclear." (PMID 33150070, 2020). "Therefore, we speculated that IGSF10 might mechanistically regulate the growth of breast cancer cells through the mTORC1 and PI3K/Akt/mTOR signaling pathways." (PMID 33150070, 2020). "Thus, IGSF10 may be a prognostic biomarker for breast cancer." (PMID 33150070, 2020). "Interestingly, in the subgroup analysis, IGSF10 expression was significantly correlated with OS in patients with basal, luminal A and HER2-positive breast cancer." (PMID 33150070, 2020). "The multivariate analysis identified that IGSF10 as an independent prognostic factor for the OS (hazard ratio (HR) = 1.793, 95% confidence interval (CI) [1.141–2.815], P = 0.011) and RFS (HR = 2.298, 95% CI [1.317–4.010], P = 0.003) of patients with breast cancer." (PMID 33150070, 2020). "Low IGSF10 expression was significantly correlated with a shorter OS of patients with basal (HR = 0.44, 95% CI [0.22–0.86], P = 0.013), luminal A (HR = 0.47, 95% CI [0.25–0.88], P = 0.017), and HER2+ (HR = 0.28, 95% CI [0.09–0.81], P = 0.012) breast cancer subtypes." (PMID 33150070, 2020). "However, the biological roles of IGSF10 in the majority of cancers have not been investigated, and its role in breast cancer remains largely unknown." (PMID 33150070, 2020).
gastric cancer (4 papers, 2016 to 2025). A primary or metastatic malignant neoplasm involving the stomach. "Moreover, IGSF10 mutations are associated with endometrial cancer and gastric cancer." (PMID 34351868, 2021). "We found that IGSF10 was a low-risk gene in BRCA, LUAD, and LUSC, while it was a high-risk gene in BLCA, Gastric cancer (GC), and Colorectal cancer (CRC)." (PMID 36685968, 2022). "IGSF10 regulates T cell function via the Spi-B/Integrin-β1 pathway, where its low expression correlates with poor prognosis, mirroring PD-1/PD-L1 dynamics in gastric cancer immunotherapy." (PMID 40598621, 2025). "The IGSF10 gene has not been described in relation to colorectal or gastric cancer but is a gene involved in differentiation and developmental processes, and possibly involved in rat osteosarcomas." (PMID 26872740, 2016).
lung adenocarcinoma (4 papers, 2021 to 2025). A carcinoma that arises from the lung and is characterized by the presence of malignant glandular epithelial cells. "This suggests that in the future, we can combine IGSF10 restoration strategies with CD47/CD276 blockade to inhibit the progression of lung adenocarcinoma." (PMID 41447338, 2025). "From the level of IGSF10 in normal cells and lung adenocarcinoma cells, the expression of IGSF10 in lung adenocarcinoma cells was lower than that in normal cells." (PMID 41447338, 2025). "This study revealed that low expression of IGSF10, an important member of the immunoglobulin superfamily, significantly correlates with poor overall survival of lung adenocarcinoma (LUAD) patients and strong tumorigenic capacity of LUAD cells." (PMID 41447338, 2025). "In this study, we investigated the mechanistic role and prognostic significance of IGSF10 in lung adenocarcinoma." (PMID 34351868, 2021). "Oncomine database analysis showed that IGSF10 expression was significantly reduced in most cancer types, including lung adenocarcinoma (LUAD)." (PMID 34351868, 2021). "Therefore, in this study, we performed bioinformatics analysis and in vitro experiments to determine the prognostic significance and mechanistic role of IGSF10 in lung adenocarcinoma (LUAD)." (PMID 34351868, 2021). "We also investigated the relationship between IGSF10 and miR-106b-5p in lung adenocarcinoma (LUAD)." (PMID 34351868, 2021). "In this study, four key biomarkers closely related to mesenchymal stem cell proliferation/differentiation (MSCPD) were identified in lung adenocarcinoma (LUAD), namely MS4A2, IGSF10, NTRK3, and MFAP3L." (PMID 40598621, 2025).
hypogonadotropic hypogonadism (3 papers, 2016 to 2020). Abnormal ovarian or testicular function due to insufficient hormonal stimulation from the hypothalamic-pituitary axis. "Another likely pathogenic variant was found in the IGSF10 gene, which is a player recently evidenced to be causative for isolated hypogonadotropic hypogonadism and delayed puberty." (PMID 32612575, 2020). "Our evidence strongly suggests that mutations in IGSF10 cause DP in humans, and points to a common genetic basis for conditions of functional hypogonadotropic hypogonadism (HH)." (PMID 27137492, 2016). "In addition, loss-of-function mutations in IGSF10 were found in patients with a hypothalamic amenorrhea-like phenotype, implying a shared genetic basis of functional central hypogonadism with both CHH and delayed puberty." (PMID 31293522, 2019). "Furthermore, mutations in IGSF10 may contribute to the phenotype of other forms of secondary hypogonadism." (PMID 27137492, 2016). "However, although deleterious mutations were enriched in CHH patients, there was lack of complete segregation with trait in these permanent hypogonadotropic hypogonadism families, suggesting that haploinsufficiency of IGSF10 is not sufficient to cause this phenotype." (PMID 31293522, 2019).
cervical cancer (2 papers, 2017 to 2023). A primary or metastatic malignant neoplasm involving the cervix. "In cluster 1/2, the incidence of FLG, BIRC6, and IGSF10 mutations were significantly higher, and it is reported that FLG contributes to the biological activity of barrier function and associates with the poor prognosis of cervical cancer." (PMID 37735483, 2023).
congenital hypogonadotropic hypogonadism (2 papers, 2021 to 2025). Congenital hypogonadotropic hypogonadism (CHH) is a rare disorder of sexual maturation characterized by gonadotropin (Gn) deficiency with low sex steroid levels associated with low levels of follicle stimulating hormone (FSH) and luteinizing hormone (LH). "For example, IGSF10 mutations can result in delayed puberty via dysregulating gonadotropin‐releasing hormone (GnRH) neuronal migration and IGSF10 deficiency‐triggered transient GnRH deficiency may lead to a reversible congenital hypogonadotropic hypogonadism (CHH)." (PMID 41447338, 2025). "A role for IGSF10 in CCD has not been previously reported, though pathogenic IGSF10 mutations have been detected in self-limited delayed puberty (DP) and congenital hypogonadotropic hypogonadism (CHH)." (PMID 34737766, 2021).